TLR4 (toll like receptor 4)
Diseases named in the same sentence as TLR4 in open-access papers (continued):
Sharing a sentence is not in itself a finding about the gene and the disease.
Sepsis (continued). "Anti-TLR4 antibodies have been investigated in animal models of sepsis, with a reported benefit in certain studies, though a recent paper suggested no survival benefit in an Escherichia coli-induced abdominal sepsis model in mice." (PMID 25722880, 2015). "Here, we evaluated the effects of preventive or therapeutic administration of monoclonal antibodies (mAbs) targeting either TLR2 or TLR4 in a model of severe polymicrobial sepsis induced by cecal ligation and puncture in mice." (PMID 26147469, 2015). "The present study also shows that delayed kallistatin administration decreased sepsis-induced TLR4 expression in the lung and liver." (PMID 25930108, 2015). "During an in vitro experiments with human DCs and TLR4-transfected Jurkat cells, the CyP molecule prevented Neisseria meningitidis LPS from binding to TLR4, lowering inflammatory response and preventing septicemia." (PMID 26198237, 2015). "KB possesses anti-inflammatory activity, as demonstrated by its ability to inhibit the inflammatory response in mouse macrophages, rescue mice from heat-killed E. coli-induced sepsis and prevent the upregulation of TLR4 and TLR9 expression." (PMID 25667619, 2015). "Compared with sham group, CLP-induced sepsis dramatically increased TLR4 and MyD88 mRNA expression in both CLP and yohimibine groups (P < 0.01)." (PMID 25929655, 2015). "In summary, this study demonstrated that CLP-induced sepsis promoted the expression of TLR4 and Myd88 and the activation of ERK1/2 and NF-κB in lung tissue, and ultimately induced the generation of TNF-α and IL-6 in BALF and plasma." (PMID 25929655, 2015). "Current research on TLR4 signaling is concentrated in the areas of infectious disease, pulmonary infections, cancer, type 2 diabetes, and sepsis." (PMID 26576220, 2015). "Lipopolysaccharides (LPS) can induce acute inflammation, sepsis, or chronic inflammatory disorders through the Toll receptor 4 (TLR4) signaling pathway." (PMID 26512658, 2015). "Since the generationof IL-6 and TNF-α is highly relevant to LPS/TLR4/MyD88/MAPK/NF-κB signal pathway in sepsis, therefore, we verified the effect of dexmedetomidine on these signal molecules in CLP-induced septic rats." (PMID 25929655, 2015). "TLR4 signaling is dependent on MyD88, which has been examined as an exciting potential therapeutic target for the treatment of sepsis." (PMID 25722880, 2015). "The TLR4 signaling pathway leading to LPS-mediated NF-kappa B activation constitutes an important therapeutic target for sepsis therapy." (PMID 26798659, 2015). "The uncontrolled inflammatory response of TLR4 leads to autoimmune diseases such as sepsis, and thus the less virulent marine cyanobacterial LPS molecules can be effective to inhibit TLR4 signaling." (PMID 26198237, 2015). "Protective effects were observed even when the administration of either anti-TLR2 or anti-TLR4 alone was delayed (i.e., 3 h after sepsis induction)." (PMID 26147469, 2015). "In CLP sepsis, there was a two-fold increase in the frequency of the TLR4-positive CD34+ CD38− cells (55 ± 13.4 % versus 26.1 ± 13.4 %)." (PMID 26272069, 2015). "Tim-3 has also been proved to negatively regulate the toll-like receptor 4 (TLR-4)-mediated immune responses and plays important roles in maintaining the homeostasis of sepsis." (PMID 25337993, 2014). "The current results are partly in contrast to the recent clinical trial using a TLR4 antagonist in sepsis." (PMID 25182709, 2014). "Tim-3 pathway has also been demonstrated to negatively regulate TLR-4 responses, resulting in down-regulation of the excessive inflammatory response and promoting the homeostasis of sepsis." (PMID 25337993, 2014). "During situations of sepsis, the liver is the main site of clearance of increased levels of LPS from the blood stream, and we have previously shown that hepatocyte TLR4 plays a vital role in this process." (PMID 24683544, 2014).
Sepsis (continued). "The aim of this study was to investigate the associations between expression of TLR2, TLR4 and TLR9 and occurrence of sepsis in patients treated with intensive induction chemotherapy for AML." (PMID 25412934, 2014). "Initial clinical trials also showed beneficial effects of blocking TLR4 in sepsis, but in larger follow-up investigations, survival was not improved." (PMID 25182709, 2014). "It was found that TLR4 and complement system are involved in the initiation of the inflammatory response in sepsis." (PMID 25870671, 2014). "Due to their low stimulatory potential, these lipid A molecules are suggested to be applicable as antagonists of TLR4 signaling in sepsis patients, where this immune response is amplified and unregulated." (PMID 25056632, 2014). "In this study we have shown the importance of T-cells in the protective effect of TLR4 stimulation in the setting of experimental sepsis." (PMID 24465843, 2014). "The primary endpoint, organ failure, was quantified using SOFA scores as a specific clinical marker in patients with sepsis and was significantly higher in TLR4 rs11536889 GG patients compared with those of TLR4 rs11536889 GC and CC patients." (PMID 24950711, 2014). "It is recognized that downregulation of MFG-E8 production during sepsis is primarily dependent on activation of the LPS-CD14-TLR4 pathway, and that phagocytosis of apoptotic cells is associated with the TLR4-MFG-E8 pathway." (PMID 24645646, 2014). "We previously showed that ALI secondary to sepsis was milder in alloxan-induced diabetic rats and involved the adaptor molecule of the IL-1 receptor family (which includes TLR-4), MyD88." (PMID 25398720, 2014). "Sepsis is a clinical syndrome that originates from the TLR4 response, and therefore, future therapies focus on the elements of this signaling pathway." (PMID 25056632, 2014). "LPS is classically utilized as a model of inflammation and sepsis, with effects via toll-like receptor 4 (TLR4)." (PMID 25551197, 2014). "On the other hand regulation of TLR4 activity breaks down during Gram −ve sepsis leading to systemic damage, multi organ failure, and death." (PMID 25339952, 2014). "Since TLR4 antagonists are proposed to enter clinical trails for treatment sepsis as well as neuropathic pain a careful evaluation of these is important for the design of the studies." (PMID 24499354, 2014). "The rs11536889 polymorphism in TLR4 and rs2563298 polymorphism in CD14 were significantly associated with the risk of sepsis when compared to the control group." (PMID 25394369, 2014). "Our present findings are in accordance with a previous work on TLR4 expression in patients with sepsis, that revealed early TLR4-protein down-regulation, using flow cytometry." (PMID 24491080, 2014). "In this study, we investigated the relationship between sepsis and TLR4 gene rs10759932, rs11536889, rs7873784, rs12377632, rs1927907 and rs1153879 polymorphisms as well as CD14 gene rs2563298 and rs2569190 polymorphisms in a Chinese population." (PMID 25394369, 2014). "These peptides were also shown to be able to block TLR4 signaling in vivo, showing the potential to be used in future therapies against sepsis." (PMID 25056632, 2014). "The aim of our study was to investigate the possible associations between expression of TLR2, TLR4 and TLR9 and occurrence of sepsis in patients treated with intensive induction chemotherapy for AML." (PMID 25412934, 2014). "Similar to HMGB1, large amounts of MIF are released during sepsis, which promotes a pro-inflammatory response by amplifying cytokine secretion through the upregulation of TLR4 expression." (PMID 25870671, 2014). "The rs11536889 polymorphism in TLR4 and rs2563298 polymorphism in CD14, and two haplotypes were associated with increased susceptibility to sepsis." (PMID 25394369, 2014).
Sepsis (continued). "In this study, we investigated the association of TLR4 gene and CD14 gene SNPs (TLR4: rs10759932, rs11536889, rs7873784, rs12377632, rs1927907, rs1153879 and CD14: rs2563298, rs2569190) with susceptibility to sepsis." (PMID 25394369, 2014). "This new delivery protocol has considerable therapeutic potential as shown in our model of sepsis-induced acute lung injury induced by intratracheal lipopolysaccharide (LPS) injection in C3H/HeN (TLR4+/+) and C3H/HeJ (TLR4–/–) mice." (PMID 24814863, 2014). "In summary, this study indicates that SNPs (TLR4: rs 11536889 and CD14: rs2563298) and two haplotypes are associated with susceptibility to sepsis in a Chinese population." (PMID 25394369, 2014). "A recent phase 2 trial found a nonsignificant trend toward better survival in patients with severe sepsis treated with eritoran tetrasodium, a TLR-4 antagonist." (PMID 24249974, 2013). "In the following sections, we present the most advanced TLR4 antagonists developed for the treatment of sepsis." (PMID 24302927, 2013). "Gastrin-releasing peptide receptor (GRPR) is linked to TLR4 signaling and antagonistic blockade of GRPR leads to limited protection from lethal sepsis." (PMID 24086587, 2013). "It has been reported that TLR2 and TLR4 are regulated in the lung, liver, and spleen in mice suffering from polymicrobial sepsis." (PMID 23935245, 2013). "TLR4 expression is increased in human monocytes of healthy volunteers challenged with LPS, as well as in patients with sepsis." (PMID 24302927, 2013). "Great deal of effort has been invested particularly into the development of TLR4 antagonists for sepsis and antibodies against TLR2 or TLR4 have shown some promising results for the therapy of sepsis." (PMID 23305364, 2012). "In a similar way, it has been shown that HA exhibits a CD44-dependent protection against LPS-induced murine sepsis by binding to TLR4 and blocking excessive inflammatory cytokine production." (PMID 22721434, 2012). "When considered as a whole, our data suggest that SRA plays a key role in the morbidity and mortality of sepsis via its interaction with TLR4." (PMID 23071440, 2012). "Intracellular levels of TLR2 and TLR4, in both CD56bright and CD56dim NK cell subsets from sepsis patients, were increased compared to healthy subjects." (PMID 23098236, 2012). "The experiments of this study demonstrated that TLR4-deficiency protected partly and TLR9- as well as CD14-deficiency protected completely from sepsis-induced vasoplegia." (PMID 22970242, 2012). "In the kidneys of animals with sepsis, there is marked upregulation of TLR4, which is known to stimulate production of the pro-inflammatory transcription factor nuclear factor kappa B (NF-κB)." (PMID 22235348, 2012). "Mechanistically, SRA interacts with TLR4 to enhance the development of the pro-inflammatory phenotype and mediate the morbidity and mortality of sepsis/septic shock." (PMID 23071440, 2012). "Initially, we observed that there was an up-regulation of TLR2, TLR4 and MyD88 in the WT mice that were subjected to sepsis." (PMID 22655058, 2012). "Our data suggest that the interaction of SRA with TLR4 amplifies the signal generated by TLR4 in response to the bacterial and endogenous ligands released during polymicrobial sepsis." (PMID 23071440, 2012). "In the canine patient the role of TLR4 during sepsis and the related systemic inflammatory response syndrome has still not been investigated." (PMID 23016675, 2012). "Specifically, SRA interacts with TLR4 thereby facilitating the development of the pro-inflammatory phenotype and mediating the morbidity and mortality of sepsis/septic shock." (PMID 23071440, 2012). "• Intracellular expression of TLR2 and TLR4 in both CD56Dim and CD56Bright NK cell subsets is enhanced during sepsis." (PMID 23098236, 2012). "TLR2-D animals are more prone to polymicrobial sepsis, presumably due to up-regulation of TLR4, 9 and CD14." (PMID 22970242, 2012).
Sepsis (continued). "C57BL/6 TLR2−/−, TLR4−/− and MyD88−/− male mice were subjected to sepsis by cecal ligation and puncture (CLP)." (PMID 22655058, 2012). "Dysregulated or excessive response to bacterial endotoxin recognized by the TLR4/MD-2 (myeloid differentiation factor 2) complex results in the systemic inflammatory reaction which often leads to sepsis with high mortality." (PMID 23305364, 2012). "Nevertheless, it is of interest to note that the percentage of positive cells for surface TLR4 expression on NK cells allows discrimination of patients with sepsis and SIRS." (PMID 23098236, 2012). "As one of the most important transcription factors in the TLR4 signaling pathway, NF-κB plays a critical role in the pathophysiology of sepsis." (PMID 22235348, 2012). "In contrast, intracellular TLR4 expression was significantly enhanced in sepsis patients and SIRS patients compared to healthy controls in both NK subsets." (PMID 23098236, 2012). "Although the relationship between TLR4 and NF-κB activation remains hypothetical, we found indirect evidence that EpoR activation plays a role in sepsis-mediated inflammation." (PMID 22235348, 2012). "In studies focusing on infection or sepsis, associations have been described for SNPs in the TLR1 (rs5743551), TLR2 (rs5743708), TLR4 (rs4986790 and rs4986791), TLR9 (rs5743836), IRAK1 (rs1059703), and TIRAP genes (rs8177374 and rs7932766)." (PMID 21219635, 2011). "Hepatic VLCAD levels decreased in WT and especially in TLR2−/− mice in sepsis, but increased in TLR4−/− mice relative to the outer membrane reference protein porin." (PMID 21966468, 2011). "The role of TLR4 in sepsis-induced cardiac dysfunction has been studied mainly in endotoxemic models." (PMID 21977329, 2011). "In particular, their ability to modulate TLR-4 expression is being investigated in the treatment of sepsis and septic shock." (PMID 21352551, 2011). "Recent work has established the contribution of toll-like receptor 4 (TLR4) activation to several brain pathologies including ischemia, neurodegeneration and sepsis." (PMID 21385378, 2011). "Five genes, namely TLR2, TLR4, TLR9, MyD88 and TOLLIP, were investigated for their association with sepsis susceptibility by a tag single nucleotide polymorphism (SNP) strategy." (PMID 21219635, 2011). "A recent phase 2 trial evaluated the efficacy of the TLR-4 antagonist eritoran tetrasodium for the treatment of sepsis in normal weight patients (~86 kg)." (PMID 20958969, 2010). "A better knowledge of TLR4 regulation molecules will be crucial to control host to infection reaction and avoid the detrimental consequences of sepsis." (PMID 20396414, 2010). "Any compound able at increasing this natural soluble TLR4 would thus be of potential interest in treating patients with sepsis." (PMID 20396414, 2010). "Since most of the clinical trial targeting single inflammatory cytokine in the treatment of sepsis failed, therapeutic targeting of Toll-like receptor 4, because of its central role, looks promising." (PMID 20396414, 2010). "The TLR4 signalling pathway leading to lipopolysaccharide-mediated NF-κB activation constitutes an important therapeutic target for sepsis therapy." (PMID 20396414, 2010). "The purpose of this paper is to focus on the recent data of various drugs targeting TLR4 expression and pathway and their potential role as adjunctive therapy in severe sepsis and septic shock." (PMID 20396414, 2010). "In contrast to downregulation of TLR gene expression after LPS exposure in cell culture, sepsis in mice and humans sepsis causes an upregulation of TLR2, TLR4 and CD14 expression on blood monocytes." (PMID 19371402, 2009). "The studies reviewed here demonstrate that TLR4 not only plays a role as a mediator of cardiac dysfunction in sepsis, but also serves as a key mediator of myocardial injury and inflammation in the setting of I/R." (PMID 20676278, 2009).
Sepsis (continued). "Protein expression of CD14, TLR2 and TLR4 on blood monocytes was examined using flow cytometry from 29 patients with sepsis and 14 healthy controls." (PMID 19371402, 2009). "We found an increased expression of CD14, TLR2 and TLR4 in patients with sepsis compared to controls (p < 0.01)." (PMID 19371402, 2009). "As shown by other investigators before, CD14, TLR2 and TLR4 protein expression on monocytes is elevated during sepsis." (PMID 19371402, 2009). "Accordingly, recent findings have demonstrated that TLR4 not only plays a central role as a mediator of cardiac dysfunction in sepsis, but also serves as a key mediator of myocardial injury and inflammation in the setting of I/R." (PMID 20676278, 2009). "In the present study, we evaluated the expression of TLR2, TLR4, CD11b, CD11c and CD66b on the cell surface of neutrophils in patients with sepsis, severe sepsis and septic shock, and compared the findings with those from healthy volunteers." (PMID 18302745, 2008). "Several single-nucleotide polymorphisms (SNPs) have been identified in the TLR4 gene, some of which are strongly associated with increased susceptibility to Gram-negative bacterial infections and an increased incidence of sepsis." (PMID 41598258, 2026). "The same study found an association between the TLR4-Asp299Gly polymorphism A/A-variant and infection with Acinetobacter baumannii (p = 0.001), non-specific Gram-negative bacilli infection, and sepsis in the adult population." (PMID 41598258, 2026). "Additionally, the tripeptide RKH, derived from A. muciniphila, functions as a novel TLR4 antagonist, offering significant protective effects against lethal sepsis." (PMID 40761792, 2025). "What's more, in sepsis or aseptic inflammation, overexpressed TLR4 was related to the increased production of CCL1 and CXCL8 in order to recruit monocytes to the sites of infection 34, which was contrary to the inhibited chemotaxis of TLR4high monocytes in our patients with heatstroke." (PMID 40084252, 2025). "The TLR4-induced PDPNhi PM subpopulation is endowed with enhanced phagocytic activity, is akin to an M2 phenotype, and plays a direct role in protecting against bacterial infection in sepsis." (PMID 39903516, 2025). "TLR4 inhibition reduces the release of inflammatory cytokines and mortality during sepsis in mice." (PMID 39853914, 2025). "A NALB/c inbred male mice was studied as in vivo model of sepsis and observed that luteolin was found to have a role in inhibition of phagocytosis of macrophages, downregulation in expression of myeloid differentiation factor 88 (MyD88) and TLR4." (PMID 39830909, 2025). "Furthermore, the blockade of TLR2 or TLR4 signaling by antagonistic antibodies or small molecule inhibitors successfully decreases disease severity in sepsis mouse models 13-15." (PMID 40963927, 2025). "Thus, modulation of TLR4 signaling is considered a promising therapeutic strategy for sepsis-induced AKI." (PMID 40869248, 2025). "TAK-242, a TLR4 antagonist, has shown promise as adjunct therapy for thrombocytopenia in sepsis by mitigating LPS-induced systemic inflammation, thus reducing end-organ damage and slowing sepsis progression." (PMID 40003683, 2025). "While the potential for circadian rhythm change in TLR4 production during modelled sepsis is unmapped, the TLR4 increase during the active phase may be integral to circadian-dependent effects of mortality in murine models of sepsis." (PMID 39968295, 2025). "Notably, the suppression of the TLR4/ MAPK/ NF-κB signaling pathway was identified as a pivotal mechanism, corroborating its established involvement in sepsis-associated endothelial activation." (PMID 40524158, 2025). "Induction of podoplanin (PDPN) expression is a critical response of macrophages to LPS stimulation or bacterial infection in sepsis, but how this key process of TLR4-stimulated PDPN upregulation is regulated and the effect of PDPN expression on macrophage function remain elusive." (PMID 39903516, 2025).